PRR5 (proline rich 5)
Description:
Associated subunit of mTORC2, which regulates cell growth and survival in response to hormonal signals. mTORC2 is activated by growth factors, but, in contrast to mTORC1, seems to be nutrient-insensitive. mTORC2 seems to function upstream of Rho GTPases to regulate the actin cytoskeleton, probably by activating one or more Rho-type guanine nucleotide exchange factors. PRR5 plays an important role in regulation of PDGFRB expression and in modulation of platelet-derived growth factor signaling. May act as a tumor suppressor in breast cancer.
Synonyms: Protor-1; PROTOR1; PP610; FLJ20185k; Protor-1.
Tractability: PROTAC: ubiquitination databases record sites on it.
Gene: Protein-coding gene on chromosome 22 (44,668,547 to 44,737,681, forward strand). Ensembl gene ENSG00000186654.
Pathways (Reactome):
Disease: Constitutive Signaling by AKT1 E17K in Cancer; Dengue virus modulates apoptosis
Signal Transduction: PIP3 activates AKT signaling; VEGFR2 mediated vascular permeability
Cellular responses to stimuli: High laminar flow shear stress activates signaling by PIEZO1 and PECAM1:CDH5:KDR in endothelial cells
Immune System: CD28 dependent PI3K/Akt signaling
Gene Ontology:
Molecular function: protein binding
Biological process: cellular response to nutrient levels; cytoskeleton organization; negative regulation of apoptotic process; positive regulation of cell growth; TORC2 signaling
Cellular component: TORC2 complex; cytosol
Genetic constraint (gnomAD): Loss-of-function variants: 25 observed, 28.81 expected, observed/expected ratio (o/e) 0.87, 90% interval 0.63 to 1.21. The synonymous counts are far from expectation, so gnomAD's model fits this gene poorly and the ratio says little. Missense variants: 600 observed, 514.42 expected, observed/expected ratio (o/e) 1.17, 90% interval 1.09 to 1.25. Synonymous variants: 286 observed, 232.33 expected, observed/expected ratio (o/e) 1.23, 90% interval 1.12 to 1.36.
Homologues: Orthologues: chimpanzee PRR5 (99% identical), macaque PRR5 (96% identical), pig PRR5 (90% identical), mouse Prr5 (89% identical), rat Prr5 (87% identical), guinea pig PRR5 (79% identical), dog PRR5 (74% identical), tropical clawed frog prr5 (71% identical), zebrafish prr5a (61% identical), zebrafish prr5b (23% identical). Paralogues in human: PRR5L (36% identical).
Diseases named in the same sentence as PRR5 in open-access papers:
PRR5 is named in the same sentence as 15 diseases in open-access papers, as found by Europe PMC text mining. Sharing a sentence is not in itself a finding about the gene and the disease. The quoted sentences say what the papers report.
Obesity (2 papers, 2018 to 2023). Accumulation of substantial excess body fat. "PRR5 (mapped with cg008870527) is a component of the (mTOR) complex 2 which is upstream of major pathways known to have a crucial role in metabolic regulation and is suggested to play a role in obesity and the pathogenesis of insulin resistance." (PMID 37649101, 2023).
breast carcinoma (1 paper, 2020). "Hypermethylated PRR5, an established tumor suppressor gene in breast cancer, is a component of mTOR complex 2 which acts as a central regulator of cell growth and survival in response to hormonal signals." (PMID 32051475, 2020).
emphysema (1 paper, 2021). "The cytosolic transport (RNF126, PLEKHJ1, VPS51, and AP1G1), target of rapamycin (mTOR) signaling (PIK3CA, STK11, RPS6KB2, and PRR5), regulation of translation, metabolic regulation, and apoptosis are involved in the percent emphysema-associated network." (PMID 34777474, 2021).
epilepsy (1 paper, 2025). A brain disorder characterized by episodes of abnormally increased neuronal discharge resulting in transient episodes of sensory or motor neurological dysfunction, or psychic dysfunction. "Dysregulation of mTORC2 signaling, including the PRR5 component, can contribute to abnormal neuronal growth and reorganization, which may play a role in the development of epilepsy and its progression." (PMID 40217352, 2025).
gastric cancer (1 paper, 2016). A primary or metastatic malignant neoplasm involving the stomach. "Among the candidates, we focused on three read‐through transcription candidates that included gastric cancer‐related genes (PHOSPHO2‐KLHL23, RPL17‐C18orf32, PRR5‐ARHGAP8)." (PMID 27833855, 2016). "We screened read‐through transcription events from stomach adenocarcinoma RNA‐seq data and selected three candidates PHOSPHO2‐KLHL23, RPL17‐C18orf32, and PRR5‐ARHGAP8, to assess their biological role in gastric cancer." (PMID 27833855, 2016).
multiple sclerosis (1 paper, 2024). A progressive autoimmune disorder affecting the central nervous system resulting in demyelination. "BACH1 has been proposed as a therapeutic target for several neurological diseases (e.g., Parkinson’s disease, multiple sclerosis), and PRR5 is part of the mTORC2 protein complex that is decreased in the AD brain at the protein level." (PMID 38557897, 2024).
pituitary adenomas (1 paper, 2025). "Additional genes—PHYHD1, LTBR, MYBPHL, C22orf42, PRR5, ANKDD1A, RAB13, CAMKV, KIFC3, WNT4, and STAT6—were implicated in the invasive behavior of non-functioning pituitary adenomas (NFPAs)." (PMID 39859246, 2025).
tumor (4 papers, 2016 to 2020). "The DNA methylation and expression levels of PHYHD1, LTBR, MYBPHL, C22orf42, PRR5, ANKDD1A, RAB13, CAMKV, KIFC3, WNT4 and STAT6 are associated with tumor invasion, and these genes may become the potential genes for targeted therapy." (PMID 31796052, 2019). "The expression levels of PRR5‐ARHGAP8 and its proximal gene were also higher in tumor samples than in normal tissues, whereas its distal gene expression was not elevated." (PMID 27833855, 2016).
cancer (3 papers, 2020 to 2023). A tumor composed of atypical neoplastic, often pleomorphic cells that invade other tissues. "Six pDGVs in the PINX1, MOB1A, CLTCL1, PRR5, CCDC136, and TRIM32 genes involved the exact amino acid residues affected by known somatic cancer variants." (PMID 33273457, 2020). "Further pan-cancer analyses show positive correlations between the expression of RICTOR and the top 10 interacting genes in the majority of cancer types, except for gene PRR5 with negative correlation." (PMID 37372460, 2023).
digestive tumours (1 paper, 2024). "Our analysis of PPI networks identified 11 hub genes (Myd88, Traf6, Irf7, Cdk4, Ccnd2, Mapkap1, Prr5, Mpp3, Serpinb6b and Pvrl3) that were implicated in digestive tumours." (PMID 38434966, 2024). "The PPI networks identified 10 hub genes that were implicated in digestive tumour immunotherapy target TIM-3 (Myd88, Traf6, Irf7, Cdk4, Ccnd2, Mapkap1, Prr5, Mpp3, Serpinb6b and Pvrl3)." (PMID 38434966, 2024).
PRR5 also shares sentences with these, for which no sentence is quoted: bipolar disorder (1 paper); Insulin resistance (1); neurological diseases (1); Parkinson disease (1); stomach adenocarcinoma (1).